PSMD1 (proteasome 26S subunit, non-ATPase 1)
Description:
Component of the 26S proteasome, a multiprotein complex involved in the ATP-dependent degradation of ubiquitinated proteins. This complex plays a key role in the maintenance of protein homeostasis by removing misfolded or damaged proteins, which could impair cellular functions, and by removing proteins whose functions are no longer required. Therefore, the proteasome participates in numerous cellular processes, including cell cycle progression, apoptosis, or DNA damage repair.
Synonyms: S1; P112; Rpn2
Tractability: Small molecule: an approved drug acts on it; a structure with a bound ligand is known; a high-quality ligand is known. Antibody: its Gene Ontology location is reachable by antibodies, with high confidence. PROTAC: ubiquitination databases record sites on it; its protein half-life has been measured.
Target class: Other cytosolic protein
Gene: Protein-coding gene on chromosome 2 (231,056,845 to 231,173,116, forward strand). Ensembl gene ENSG00000173692.
Subcellular location (Human Protein Atlas): Nucleoplasm; Actin filaments
Pathways (Reactome):
Immune System: AMPK-induced ERAD and lysosome mediated degradation of PD-L1(CD274); Activation of NF-kappaB in B cells; Antigen processing: Ubiquitination & Proteasome degradation; CLEC7A (Dectin-1) signaling; Cross-presentation of soluble exogenous antigens (endosomes); Dectin-1 mediated noncanonical NF-kB signaling; Downstream TCR signaling; ER-Phagosome pathway; FCERI mediated NF-kB activation; GSK3B-mediated proteasomal degradation of PD-L1(CD274); Interleukin-1 signaling; NIK-->noncanonical NF-kB signaling; Neutrophil degranulation; SPOP-mediated proteasomal degradation of PD-L1(CD274); TNFR2 non-canonical NF-kB pathway
Cell Cycle: APC/C:Cdc20 mediated degradation of Securin; APC/C:Cdh1 mediated degradation of Cdc20 and other APC/C:Cdh1 targeted proteins in late mitosis/early G1; Autodegradation of Cdh1 by Cdh1:APC/C; Autodegradation of the E3 ubiquitin ligase COP1; Cdc20:Phospho-APC/C mediated degradation of Cyclin A; FBXL7 down-regulates AURKA during mitotic entry and in early mitosis; G2/M Checkpoints; SCF(Skp2)-mediated degradation of p27/p21; SCF-beta-TrCP mediated degradation of Emi1; Separation of Sister Chromatids; The role of GTSE1 in G2/M progression after G2 checkpoint; Ubiquitin-Mediated Degradation of Phosphorylated Cdc25A; Ubiquitin-dependent degradation of Cyclin D
Signal Transduction: Asymmetric localization of PCP proteins; Degradation of AXIN; Degradation of DVL; Degradation of GLI1 by the proteasome; Degradation of GLI2 by the proteasome; Degradation of beta-catenin by the destruction complex; GLI3 is processed to GLI3R by the proteasome; Hedgehog 'on' state; Hedgehog ligand biogenesis; MAPK6/MAPK4 signaling; Negative regulation of NOTCH4 signaling; Regulation of PTEN stability and activity
and 28 more pathways
Gene Ontology:
Molecular function: protein binding; ubiquitin protein ligase binding; enzyme regulator activity
Biological process: cellular response to type I interferon; proteasomal protein catabolic process; proteasome-mediated ubiquitin-dependent protein catabolic process; regulation of proteasomal protein catabolic process; response to oxidative stress; regulation of protein catabolic process
Cellular component: membrane; proteasome complex; azurophil granule lumen; cytosol; extracellular region; nucleoplasm; proteasome accessory complex; proteasome regulatory particle; proteasome storage granule; synaptic vesicle
Genetic constraint (gnomAD): Loss-of-function variants: 8 observed, 74.63 expected, observed/expected ratio (o/e) 0.11, 90% interval 0.062 to 0.19. The upper end of that interval is the gene's LOEUF score, 0.19, which puts it in group 1 of 6, group 1 being the genes least tolerant of losing a copy. Missense variants: 563 observed, 966.33 expected, observed/expected ratio (o/e) 0.58, 90% interval 0.54 to 0.62. Synonymous variants: 313 observed, 338.26 expected, observed/expected ratio (o/e) 0.93, 90% interval 0.84 to 1.02.
Homologues: Orthologues: chimpanzee PSMD1 (99% identical), macaque PSMD1 (99% identical), dog PSMD1 (99% identical), rabbit PSMD1 (99% identical), mouse Psmd1 (99% identical), pig PSMD1 (99% identical), rat Psmd1 (99% identical), guinea pig PSMD1 (99% identical), tropical clawed frog psmd1 (94% identical), zebrafish psmd1 (92% identical), Drosophila melanogaster Rpn2 (66% identical), Caenorhabditis elegans rpn-2 (37% identical). Paralogues in human: PSMD2 (19% identical).
Diseases named in the same sentence as PSMD1 in open-access papers:
PSMD1 is named in the same sentence as 127 diseases in open-access papers, as found by Europe PMC text mining. Sharing a sentence is not in itself a finding about the gene and the disease. The quoted sentences say what the papers report.
gastric cancer (22 papers, 2004 to 2025). A primary or metastatic malignant neoplasm involving the stomach. "Our finding provides a new insight for the mechanism underlying the therapeutic resistance of gastric cancer and identifies PSMD1 as a potential prognostic and therapeutic target." (PMID 31413756, 2019). "High PSMD1 expression was shown to be significantly associated with disease-free survival (DFS) and overall survival (OS) of gastric cancer patients." (PMID 37349676, 2023).
breast carcinoma (17 papers, 2016 to 2024). "Recent studies also have identified PSMD1, which encodes a subunit of the proteasome, as an upregulated factor and potential prognostic marker in several cancers including anaplastic thyroid carcinoma, breast cancer, gastric cancer, colon cancer, ovarian cancer, among others." (PMID 38104103, 2023). "For instance, it has been reported that knocking down PSMD1 in a breast cancer cell line resulted in a decrease in the S phase and an increase in the G2/M phase, indicating inhibition of the cell cycle." (PMID 38104103, 2023). "The knockdown of proteasome 26S subunit PSMD1 markedly reduced the proliferation of4-hydroxytamoxifen (OHT) resistant MCF-7 (OHTR) breast cancer cells." (PMID 31413756, 2019). "PSMD1 expression was significantly increased in all analyzed cancer tissues, including HCC, breast carcinoma, and lung, rectum, and colon adenocarcinomas, compared with that of the corresponding normal tissues." (PMID 38580756, 2024). "The levels of PSMD1, PSMD2, PSMD3, PSMD7, PSMD10, PSMD12, and PSMD14 are high in breast cancer tissue compared to normal tissues." (PMID 36934426, 2023). "At the protein level, PSMD1 was found to be upregulated in 4/5 (80%) CPTAC cancers, including breast cancer, colon cancer, clear cell renal cell carcinoma (RCC), and UCEC." (PMID 34572038, 2021). "Therefore, PSMD1 may play a role in the development of tamoxifen resistance in breast cancer cells." (PMID 31413756, 2019). "In this context, Deng and colleagues demonstrated that the expression of six proteasome subunits including PSMA1, PSMB5, PSMD1, PSMD2, PSMD8 and PSMD11 was increased over three-fold in breast cancer tissues when compared to adjacent normal tissues." (PMID 27966459, 2017). "For example, PSMD1 could regulate breast cancer cell growth, and PSMD2 can regulate tumor cell proliferation in lung cancer and breast cancer." (PMID 31703613, 2019). "The idea that PSMD1 and PSMD2 play important roles in the proliferation process of tumor cells, such as breast cancer cells and lung cancer cells, is not novel." (PMID 31703613, 2019).
pancreatic cancer (11 papers, 2005 to 2025). "Systematic evaluation of PSMD1-14 expression revealed significant upregulation (p<0.05) of PSMD1, PSMD2, PSMD3, PSMD4, PSMD7-PSMD14 transcripts in pancreatic tumor tissues compared with adjacent normal controls, with the notable exception of PSMD6 which demonstrated reduced mRNA expression." (PMID 40182048, 2025).
lung cancer (7 papers, 2019 to 2025). A malignant neoplasm involving the lung. "Sequencing found that the expression level of PSMD1 was increased in lung cancer tissues, which was the most significant difference among all genes." (PMID 41562084, 2025).
head and neck cancer (6 papers, 2016 to 2025). A primary or metastatic malignant neoplasm affecting the head and neck. "In order to establish a new cutoff for 'high expression' of PSMD1 in two head and neck cancers with limited previous studies, we plotted ROC curves using the H-scores from each location, based on the 5-year overall survival of the patients." (PMID 38104103, 2023). "Lagadecet al. showed that weak PSMD1 expression in the head and neck cancer cells predicts unfavorable outcomes post-radiotherapy." (PMID 31413756, 2019). "However, the significance of PSMD1 expression in head and neck cancer remains to be elucidated." (PMID 38104103, 2023). "However, even in TCGA open data of head and neck cancer, where there is no selection bias for gene targets and subsites, PSMD1 was confirmed as a poor prognostic factor." (PMID 38104103, 2023).
hepatocellular carcinoma (4 papers, 2014 to 2026). A malignant tumor that arises from hepatocytes. "In this study, we focused on PSMD1 to investigate its role and the molecular pathways by which it regulates the response to immunotherapy in hepatocellular carcinoma (HCC)." (PMID 41535254, 2026). "To further assess PSMD1 expression in other datasets, we used commercially available hepatocellular carcinoma cDNA and measured mRNA levels." (PMID 38580756, 2024). "The relative PSMD1 mRNA expression (PSMD1/β2-microglobulin) was significantly higher in hepatocellular carcinoma tissues (n = 23, 3.81 ± 4.36) compared with that of the corresponding normal tissues (n = 8, 1.10 ± 1.23; p = 0.012)." (PMID 38580756, 2024). "In the present study, we chose a hepatocellular carcinoma cell line, HepG2, to investigate the roles of PSMD1 and PSMD2 in cell proliferation and cellular lipid metabolism." (PMID 31703613, 2019). "To further validate the regulatory roles of PSMD1 and PSMD2 in lipid metabolism, we performed the same experiments using another human hepatocellular carcinoma cell line, Huh7." (PMID 31703613, 2019). "Therefore, the high expression levels of PSMD1 and PSMD2 probably enhanced hepatocellular carcinoma tumor cell proliferation." (PMID 31703613, 2019).
squamous cell carcinoma (4 papers, 2021 to 2025). A carcinoma arising from squamous epithelial cells. "We confirmed that PSMD1 is an independent poor prognostic factor in squamous cell carcinoma of the oropharynx, and it is closely related to HPV negativity." (PMID 38104103, 2023).
bladder cancer (3 papers, 2013 to 2020). "In this research, we mainly focus on the impacts of circRNAs on BC cell proliferation and characterize a circRNA derived from PSMD1 gene (bladder cancer related circRNA-3, BCRC-3)." (PMID 30285878, 2018). "We had analyzed circRNA high-throughout sequencing from human tissues and determined bladder cancer related circRNA-3 (BCRC-3, GenBank: KU921434.1) as a new candidate circRNA derived from PSMD1 gene." (PMID 30285878, 2018).
lung adenocarcinoma (3 papers, 2020 to 2025). A carcinoma that arises from the lung and is characterized by the presence of malignant glandular epithelial cells. "Meanwhile, research has shown that PSMD1 is overexpressed in lung adenocarcinoma." (PMID 41562084, 2025). "PSMD1 was proposed to facilitate the progression of lung adenocarcinoma." (PMID 36934426, 2023).
multiple myeloma (3 papers, 2021 to 2022). "Consistent with our findings, a previous study reported that PSMD1 or PSMD3 knockdown resulted in a greater reduction of growth in TKI-resistant multiple myeloma cells than in their TKI-sensitive counterparts." (PMID 36568232, 2022).
non-small cell lung carcinoma (3 papers, 2016 to 2025). A group of at least three distinct histological types of lung cancer, including non-small cell squamous cell carcinoma, adenocarcinoma, and large cell carcinoma. "The knockout or knockdown of PSMD1 in other cell types, including the non-small cell lung cancer cell line A549 as well as mouse (NIH 3T3), rabbit (LLC-RK), and dog (MDCK) cell lines also resulted in mitotically arrested cells with monopolar spindles." (PMID 40705606, 2025).
glioblastoma (2 papers, 2019 to 2025). The most malignant astrocytic tumor (WHO grade IV). "Staining against the proteasome subunit PSMD1, a marker correlated with worsened outcome in glioblastoma and cancer of the head and neck, was not informative because all tumor cores showed high or very high expression levels for PSMD1, thus supporting the rare nature of BCICs." (PMID 30700319, 2019). "We found loss of H3K27ac at genes related to Proteasome subunits type A, B, C and D (PSM), in particular PSMD1 and PSMD3, which have been shown to act as tumour suppressors and inhibit Wnt signalling in other cancers, though not yet described in glioblastoma." (PMID 39915814, 2025).
glioma (2 papers, 2021 to 2023). A benign or malignant brain and spinal cord tumor that arises from glial cells (astrocytes, oligodendrocytes, ependymal cells). "The mRNA levels of PSMD5/8/9/10/11/13/14 were higher in GBM than in normal brain tissues, and the mRNA levels of PSMD1/4/5/8/9/11/12 were higher in high‐grade glioma (WHO grade III & IV) than in low‐grade glioma (WHO grade II)." (PMID 37485655, 2023). "Statistically, the mRNA expression of PSMD1/4/5/8/9/11/12 tended to increase as glioma grade increased, whereas the mRNA expression of PSMD10 tended to decrease with increasing glioma grade." (PMID 37485655, 2023). "According to the TIMER2 database (glioma tissues, n = 153; adjacent normal tissues, n = 5), PSMD9/10/13/14 mRNA expression levels were significantly increased in GBM, while PSMD1 mRNA expression levels were decreased in GBM tissues." (PMID 37485655, 2023). "The mRNA expression of PSMD1/4/5/8/9/10/11/12 was significantly correlated with glioma grade, while the mRNA expression of PSMD2/3/6/7/13/14 was not correlated with glioma grade." (PMID 37485655, 2023).
liver cancer (2 papers, 2020 to 2024). An epithelial or non-epithelial malignant neoplasm that arises from the liver. "To ascertain the function of PSMD1 in cancer, we analyzed the expression and function of PSMD1 in cancer, focusing on liver cancer cells driven by distinctively increased expression and prognostic implications." (PMID 38580756, 2024).
oropharyngeal squamous cell carcinoma (2 papers, 2023 to 2025). "We aimed to assess the prognostic significance of PSMD1 expression in oropharyngeal squamous cell carcinoma (OPSCC) patients using immunohistochemistry." (PMID 38104103, 2023). "Therefore, the purpose of this study is to assess the prognostic significance of PSMD1 expression in oropharyngeal squamous cell carcinoma (OPSCC) patients using immunohistochemistry." (PMID 38104103, 2023). "In our study, we established PSMD1 as a negative prognostic factor in oropharyngeal squamous cell carcinoma, indicating its potential as a target for targeted therapy and paving the way for future in vitro studies on drug repositioning." (PMID 38104103, 2023).
ovarian carcinoma (2 papers, 2020 to 2023). A malignant neoplasm originating from the surface ovarian epithelium. "We also show that the PSMD1 depletion strategy effectively reduces primary ovarian cancer growth in mice." (PMID 36934426, 2023). "Next, we used the patient‐derived xenograft (PDX) model to treat ovarian cancer by the PSMD1 depletion strategy." (PMID 36934426, 2023). "Cell culture, mouse MDA‐MB‐231, OVCAR8 xenografts, and patient‐derived ovarian cancer xenograft (PDX) models were transduced with lentivectors expressing PSMD1 shRNA." (PMID 36934426, 2023). "Furthermore, the PSMD1 depletion strategy compromised the growth of the PDX of primary ovarian cancer." (PMID 36934426, 2023).
prostate carcinoma (2 papers, 2018 to 2024). A carcinoma that arises from epithelial cells of the prostate gland. "This conclusion was substantiated by our examination of PSMD1 and AR signalling components in a sample of six prostate cancer patients exhibiting elevated GOLM1 expression." (PMID 39470578, 2024).
breast tumor (1 paper, 2021). "Immunohistochemical (IHC) images revealed dense distributions of PSMD2 and PSMD4, while the other PSMDs, including PSMD1, PSMD2, PSMD3, PSMD7, PSMD12, and PSMD14, were moderately distributed in breast tumor samples." (PMID 34839279, 2021).
HIV-1 infection (1 paper, 2021). The type species of lentivirus and the etiologic agent of acquired immunodeficiency syndrome (AIDS). "Latency promoting factors were validated using small molecule inhibitors, characterising the role of 26S proteasome non-ATPase regulatory subunit 1 (PSMD1) in HIV-1 latency through reactivation of HIV-1 infection following treatment." (PMID 34020727, 2021).
leukemia (1 paper, 2019). A malignant (clonal) hematologic disorder, involving hematopoietic stem cells and characterized by the presence of primitive or atypical myeloid or lymphoid cells in the bone marrow and the blood. "Currently, there are no report about the relationship between PSMD1 and leukemia." (PMID 31874600, 2019).
ovary adenocarcinoma (1 paper, 2023). "We compared here the response of MDA‐MB‐231, a TNBC, and OVCAR8, high‐grade ovary adenocarcinoma, to PSMD1 depletion." (PMID 36934426, 2023).
psoriasis (1 paper, 2023). An autoimmune condition characterized by red, well-delineated plaques with silvery scales that are usually on the extensor surfaces and scalp. "Two members of the first cluster, PSMD1 and PSMD6, have previously been reported as key drivers of psoriasis in a human multi-omics study." (PMID 37521042, 2023).
spinocerebellar ataxia (1 paper, 2025). "Among the most significantly enriched proteins within the spinocerebellar ataxia pathway were proteasome 26S subunit (PSMD1, PSMD7, PSMD12, PSMD13), specifically the non-ATPase regulatory components, which are central to the degradation of ubiquitinated proteins." (PMID 41441337, 2025).
tonsillar cancer (1 paper, 2023). "PSMD1 was highly expressed in advanced pathologic staging, HPV negative tumor, and non-tonsillar cancer." (PMID 38104103, 2023).